LEP (leptin)
Diseases named in the same sentence as LEP in open-access papers (continued):
Sharing a sentence is not in itself a finding about the gene and the disease.
Obesity (continued). "Thus, the influence of these two common variants of LEP (A19G and G2548A) on obesity is inconclusive, limited by the insufficient number of available studies addressing such associations, as well as circulating levels of leptin." (PMID 35563103, 2022). "Resilient animals do not exhibit social avoidance, anhedonia-like symptoms (for example reduced sucrose consumption), or metabolic disturbances defined by over-eating, a preference for high-fat food, obesity, and obesity-associated changes (e.g., central leptin resistance)." (PMID 36362131, 2022). "The homozygous missense transition g.13289C>T, (TTA to TCA) in exon 3 of the LEP gene leading to a p.L72S protein replacement was shown to be associated with mild obesity in Australia, whereby the mutated leptin was expressed but not secreted into blood circulation." (PMID 35563103, 2022). "Contrary to HDL, TCh and LDL, positively correlated with end body weight (BW2), body weight gain (sBWG), daily (dFI) and cumulative feed intake (cFI) as well as leptin levels pointing to the causative relationship between obesity-related behavioral and metabolic parameters." (PMID 35945482, 2022). "Obesity is associated with hyperleptinemia and leptin resistance." (PMID 35269504, 2022). "We therefore investigated the expression of the seven hepatokines uncovered by our proteomic analysis in the liver of a genetic mouse models of obesity, steatosis and IR/T2D, i.e., ob/ob mice (mice deficient for leptin) and db/db mice (mice deficient for leptin receptor)." (PMID 35409319, 2022). "Associations between CRP, leptin and leptin-to-adiponectin ratio with breast cancer risk may represent the dual effect of obesity by menopausal status although this deserves further investigation." (PMID 35430795, 2022). "The development of central leptin resistance is a hallmark symptom and agitator of obesity." (PMID 36499772, 2022). "HFD-induced obesity is often associated with insulin and leptin resistance." (PMID 36226318, 2022). "Additionally, we assessed the association between LRG1 and several obesity markers, including HsCRP, chemerin, and leptin." (PMID 35955698, 2022). "Moreover, obesity is associated with a state of hyperleptinemia and decreased response to leptin which subsequently hinder leptin’s function leading to a dysregulation of energy homeostasis." (PMID 36189369, 2022). "Zinc repletion also leads to increased tissue leptin secretion, which may subsequently lead to reduced adipose tissue mass and so modify the risk of obesity." (PMID 35081959, 2022). "Leptin is potentially implicated in obesity-related cardiovascular disease." (PMID 35887911, 2022). "Also, short sleep duration is associated with hormonal imbalance including low Leptin secretion, and high Ghrelin secretion, which leads to overweight and obesity which in turn causes hypertension." (PMID 36368965, 2022). "Ob/ob mice are deficient of leptin and develop obesity with hyperphagia and hyperinsulinemia." (PMID 35851836, 2022). "It is likely that increased levels of leptin in association with its defective metabolic pathway can in part contribute to inflammatory processes and increased airway hyperreactivity, described in adult with asthma and obesity." (PMID 36291398, 2022). "Moreover, insulin resistance, hyperinsulinemia, hyperglycemia, oxidative stress, and leptin production underlie leptin’s potential role and associated mechanisms in obesity and CRC." (PMID 35563103, 2022). "In the long run, the addiction effects and leptin resistance due to the fructose increase the calorie intake because of the loss of satiety signals in the brain, which in turn, causes overweightness and obesity." (PMID 36161602, 2022).
Obesity (continued). "Leptin was one of the first adipose secreted factor discovered to play a role in appetite suppression, where humans and animals deficient in leptin exhibited hyperphagia and early onset obesity, highlighting the important endocrine role that adipose tissue plays in maintaining metabolic homeostasis." (PMID 35283789, 2022). "Patients with congenital leptin deficiency could be treated by daily injections of recombinant human leptin, which decreases obesity and associated phenotypic abnormalities." (PMID 36232301, 2022). "p62‐KO mice develop mature‐onset obesity associated with leptin resistance." (PMID 35662390, 2022). "Further, hyperleptinemia and leptin resistance are associated with obesity." (PMID 35269504, 2022). "Obesity might increase the susceptibility to harbor TAI with leptin as a peripheral determinant, which can decrease the function of regulatory T cells and increase the percentage of T helper 1 cells." (PMID 35195084, 2022). "Obesity increases the susceptibility to harbour TAI with leptin as a peripheral determinant." (PMID 34981747, 2022). "A study of young European adults concluded that the highest level of physical activity was associated with a lower fat mass, leptin and interleukin 6, and some of the detrimental influence linked with overweightness and obesity was diminished due to physical activity." (PMID 36501003, 2022). "Obesity modeling can range from using mice strains genetically deficient in leptin or its receptor ob/ob and db/db mice respectively, which gain weight even when on normal diets, or by placing different strains of mice on specific high-fat diets (HFD) to induce obesity over time." (PMID 36776393, 2022). "Thus, the regulation of leptin signalling in the course of obesity seems to be organ dependent, and particularly for the ovaries associated with the levels of obesity and pregression of the disease." (PMID 36855701, 2022). "Obesity is one of the most important risk factors for inflammatory processes in the periodontal ligament, due to elevated secretion of adipokines such as leptin." (PMID 36142638, 2022). "Leptin and adiponectin are at the top of the genes linked to obesity." (PMID 35163268, 2022). "Mutation events in the leptin gene (LEP) are associated with obesity." (PMID 35563103, 2022). "Evidence has demonstrated that sleep loss may induce leptin decrease and ghrelin increase, both of which could result in obesity." (PMID 35067221, 2022). "Besides genetic deficiency, such as leptin or leptin receptor deficiency, obesity is mainly caused by a disrupted balance of energy homeostasis with increased nutrition intake and decreased energy expenditure." (PMID 35865314, 2022). "Apart from obesity, hyperleptinemia has also been associated with hypertension and insulin resistance, while chronic hyperlipidemia is believed to exert deleterious effects on the functions of leptin." (PMID 35629157, 2022). "The low-grade chronic inflammation state associated with overweight and obesity may also interfere with food control by decreasing sensitivity to leptin." (PMID 35758834, 2022). "However, mutations that disrupt the production or bioactivity of leptin or in the gene encoding the leptin receptor are very rare and contribute to only 1–5% of severe obesity in children." (PMID 35958993, 2022). "Leptin is a plasma protein encoded by the obesity gene (ob) that was first described in 1994." (PMID 35406070, 2022). "In humans, leptin (LEP) encodes the peptide hormone leptin (homolog of the mouse obesity gene)." (PMID 36036007, 2022). "Indeed, leptin is overexpressed at the gene level in the adipose tissue of individuals with obesity and strong positive associations exist between plasma leptin levels and body fat percentage." (PMID 35958993, 2022).
Obesity (continued). "Insulin resistance and vitamin D deficiency related to obesity may aggravate airway remodeling and hyper-responsiveness by enhancing leptin, transforming growth factor (TGF)-β1, IL-1β, and IL-6 expression, which might then promote neutrophilic inflammation." (PMID 35626330, 2022). "ob/ob mice possess mutations in the leptin gene that lead to obesity." (PMID 36140261, 2022). "Mutations in the LEP gene are linked to diseases such as obesity and type II diabetes." (PMID 35647086, 2022). "Results showed that obesity caused elevated plasma glucose and leptin levels." (PMID 35208227, 2022). "In addition, cobalt can decrease obesity risk by altering lipid metabolism, such as increasing leptin; the magnitude of the effect varies according to gender." (PMID 39021719, 2022). "Similarly, we wanted to assess the effect of psilocybin in leptin-deficient ob/ob mice, a commonly used genetic model of obesity." (PMID 35953488, 2022). "Our results suggest that leptin may partly explain the reported association between obesity and kidney disease." (PMID 35619087, 2022). "The resulting loss of leptin signaling typically leads to obesity." (PMID 36125046, 2022). "In vivo and in vitro studies have demonstrated that folate deficiency increases fat accumulation and leptin production in adipocytes, which may contribute to the increase in obesity prevalence and inflammatory disease." (PMID 36079719, 2022). "However, literature regarding the association between obesity and leptin gene polymorphisms among the predominantly Dravidian population of Kerala is very scarce." (PMID 36619235, 2022). "The most typically encountered models for obesity induction are animals with genetic alterations, for example, null for the leptin gene (ob/ob), with a mutation in the leptin receptor gene (db/db, fa/fa), or fed with laboratory chow with a high percentage of fat content (high-fat diet—HFD)." (PMID 35457013, 2022). "In this study, the authors concluded that the substitution of LEP −2548 AA to AG genotypes are important predictors for increasing leptin levels and BMI in obese patients and could be a useful marker for obesity risk." (PMID 36551995, 2022). "Leptin acts as a catabolic mediator in chondrocytes and linked to obesity and OA." (PMID 35509713, 2022). "Moreover, leptin-deficient mast cells polarize macrophages from M1 to M2 and thus protects mice from obesity." (PMID 36119080, 2022). "Leptin, which is negatively associated with obesity, may lead to high serum UA levels by impairing the renal excretion of UA and downregulating the expression of hepatic xanthine oxidoreductase." (PMID 36291808, 2022). "However, and perhaps rather unexpectedly from an osteogenic viewpoint, obesity was found to be associated with enhanced leptin levels." (PMID 36105811, 2022). "On the peripheral level, increased adipose tissue, especially visceral adipose tissue, is a hallmark of obesity and acts as a major source of adipokines that are strongly correlated with headache pathogenesis, including leptin, adiponectin, and several pro-inflammatory cytokines." (PMID 36686472, 2022). "Thus, one mechanism by which obesity causes hypogonadism is via the induction of leptin resistance, leading to decreased action of KP-neurons via interneurons." (PMID 36479214, 2022). "Other obesity–cancer association mechanisms include obesity-induced chronic inflammation; increased aromatase expression, circulating levels of estrogen, insulin, leptin and ceruloplasmin; and decreased amounts of adiponectin and sex-hormone-binding globulin." (PMID 35741001, 2022). "Epigenetic regulation of the LEP gene may represent the mechanism underlying the protective effect of breastfeeding duration against obesity." (PMID 35684517, 2022).
Obesity (continued). "Moreover, rare loss-of-function mutations in the homozygous state of LEP lead to leptin deficiency, resulting in hyperphagia and severe obesity, whereas mutations in a heterozygous state result in partial leptin deficiency with higher body fat." (PMID 35563103, 2022). "The current data on LEP mutations indicate a quite different genetic profile across countries; however, only a few studies have been performed, and a common association with a severe obesity state cannot be excluded." (PMID 35563103, 2022). "Leptin inhibits food intake and functions as an anorexigen during appetite regulation in several vertebrates, including fish, and loss of function mutations in orthologous leptin genes in zebrafish and mammals increases body weight and promotes obesity." (PMID 35853004, 2022). "Therefore, when using leptin to predict fracture risk, it cannot be discussed separately from weight or obesity." (PMID 35993023, 2022). "Moreover, propionic acid stimulates the expression of the anorexigenic hormone leptin in human adipose tissue and can rescue obesity caused by a high-fat diet by inhibiting Th17-mediated intestinal inflammation." (PMID 36755580, 2022). "Epigenetic mechanisms linked to obesity that impact leptin and LEP-R expression are also at play." (PMID 34084149, 2021). "Moreover, recent evidence suggests that adipokines (such as leptin, adiponectin, and resistin) secreted in adipose mass are closely associated with insulin resistance, obesity, and an early inflammatory stage of NAFLD pathogenesis." (PMID 33758311, 2021). "Obesity might also be associated with hyperleptinaemia, which reflects a state of leptin resistance involving leptin and molecular pathways downstream of LEPR, or with leptin deficiency, which might be either complete or heterozygous." (PMID 34208585, 2021). "An increase in blood leptin level in pregnant females reduces the risk of obesity and insulin resistance inthe offspring, although the mechanisms mediating this effect are unknown." (PMID 34782887, 2021). "Underlying mechanisms of obesity on the severity of COVID-19 may involve abnormalities in the production of adipokines by AT, for example, leptin and adiponectin." (PMID 34348687, 2021). "Obesity is associated with hyperleptinaemia and leptin resistance that may also suppress the HPG axis." (PMID 34360982, 2021). "Moreover, some studies showed that testosterone (T) has immune-downregulating properties, associated with an improvement of insulin and leptin sensitivity and other parameters of obesity and MetS." (PMID 33557413, 2021). "Leptin protein was associated with miR-6803-3p negatively and all obesity indicators positively." (PMID 34440082, 2021). "In addition, in the context of obesity, a defective thermoregulatory response is associated with impaired leptin signalling overall within the ventromedial nucleus of the hypothalamus." (PMID 34208585, 2021). "Collectively, these results support that leptin may be a mediator that contributes to explain the association between obesity and both asthma persistence and control." (PMID 33418879, 2021). "We used mice and rats with diet-induced obesity fed a high-fat diet, which is considered to simulate the most common form of human obesity, or rodent models with leptin deficiency or disrupted leptin signaling in which long-term food intake regulation by leptin is distorted." (PMID 34867411, 2021). "The analysis of serum leptin level is a useful test in patients with severe early-onset obesity, but it is also plausible that mutations in the LEP gene could result in a bioinactive form of the hormone in the presence of apparently appropriate leptin levels." (PMID 34208585, 2021). "In fact, in most obesity cases, they are most often being associated with high level of leptin." (PMID 34568497, 2021).
Obesity (continued). "The previous hypothesis enunciated suggested the fact that leptin/ghrelin ratio can be used to identify subjects with an unfavorable evolution after obesity weight-loss therapeutic treatment, with weight regain after successful weight loss." (PMID 34829886, 2021). "Obesity has a more serious impact on postmenopausal women than premenopausal women suffering from breast cancer, which is caused by the different levels of estrogen secretion, and leptin plays a key role in this process." (PMID 34485124, 2021). "Up-regulation of leptin signaling could form a causal relationship with obesity-associated TNBC development by promoting CSC enrichment and EMT." (PMID 34350120, 2021). "Similarly, TSH mutations reducing the affinity of the hormone to its receptor and causing hypothyroidism, bioinactive leptin associated with obesity, and bioinactive insulin leading to MODY diabetes have all been described." (PMID 33468709, 2021). "Leptin is also associated with the low-grade inflammatory state in obesity." (PMID 34149621, 2021). "Mutation in the leptin-melanocortin pathway, polygenic obesity and epigenetic disorders like Prader-Willi and Temple syndrome play major roles in the pathogenesis of obesity." (PMID 33557185, 2021). "It is plausible that in an obesogenic environment, individuals heterozygous for LEP or LEPR variants may preferentially develop obesity with increasing age if compared to wt/wt subjects." (PMID 34448070, 2021). "Genetic factors may also influence leptin levels, since mutation in the leptin-receptor gene is associated with obesity." (PMID 35052684, 2021). "Therefore, excess accumulation of lipid droplets by leptin is thought to contribute to the obesity-linked enhanced susceptibility to colon carcinoma." (PMID 33535537, 2021). "Additionally, in cancer research, the most abundant adipokines, i.e., adiponectin and leptin, are gaining recognition as modifiable risk factors due to their links with obesity and obesity-related cancer." (PMID 34684340, 2021). "Obesity causes elevated levels of circulating leptin as consequence of leptin resistance." (PMID 34827650, 2021). "Sleep deprivation may increase the ghrelin but decrease leptin levels, causing a rise in appetite, subsequently resulting in weight gain and obesity, which is a strong risk factor for NAFLD." (PMID 34665792, 2021). "Elevated leptin concentrations are often associated with obesity or chronic diseases." (PMID 34202165, 2021). "This review provides new insight into the link between obesity, hyperleptinaemia, leptin resistance and leptin deficiency, focusing on the ability to restore leptin sensitiveness by way of enhanced thermogenic responses and highlighting novel anti-obesity therapeutic strategies." (PMID 34208585, 2021). "Previous studies have found associations between higher MOM leptin and increased infant fat mass, and some speculate that leptin may be one of the key factors in maternal-offspring obesity transmission." (PMID 34124118, 2021). "The mechanism underlying the reduction in the leptin level might be due to the anti-obesity effect of Piper sarmentosum." (PMID 34210097, 2021). "Besides, metabolic changes associated with obesity such as insulin and leptin resistance negatively impact immune cell function." (PMID 33390183, 2021). "The continuous release of proinflammatory cytokines and adipokines (e.g., leptin) by dysregulated adipose tissue may contribute to the obesity-associated inflammation." (PMID 34457110, 2021). "Furthermore, insulin also leads to the activation of leptin, an obesity related hormone, already known to associate with breast cancer progression via transcription factors including HIF1 and its crosstalk with PI3K-AKT and ERK1/2 pathways." (PMID 34225729, 2021). "Several scientific data suggest that hormonal characteristics in the prepubertal age, pro-inflammatory hormonal factors (e.g., leptin and adiponectin), and estrogen may associate asthma and obesity." (PMID 34835964, 2021).